SPDYE1 (speedy/RINGO cell cycle regulator family member E1)
Synonyms: WBSCR19; Ringo1; SPDYE; SPDYB2L2
Tractability: No criterion of Open Targets' tractability assessment is met for any kind of drug.
Gene: Protein-coding gene on chromosome 7 (43,997,897 to 44,010,124, forward strand). Ensembl gene ENSG00000136206.
Gene Ontology:
Molecular function: protein kinase binding
Genetic constraint (gnomAD): Loss-of-function variants: 28 observed, 36.81 expected, observed/expected ratio (o/e) 0.76, 90% interval 0.56 to 1.04. The upper end of that interval is the gene's LOEUF score, 1.04, which puts it in group 4 of 6, group 1 being the genes least tolerant of losing a copy. Missense variants: 326 observed, 412.34 expected, observed/expected ratio (o/e) 0.79, 90% interval 0.72 to 0.87. Synonymous variants: 128 observed, 144.1 expected, observed/expected ratio (o/e) 0.89, 90% interval 0.77 to 1.03.
Homologues: Orthologues: chimpanzee SPDYE6 (93% identical), mouse Spdye4a (35% identical), rat Spdye4 (35% identical), mouse Spdye4b (30% identical). Paralogues in human: SPDYE2 (95% identical), SPDYE2B (95% identical), SPDYE6 (95% identical), SPDYE21 (94% identical), SPDYE5 (94% identical), SPDYE18 (86% identical), SPDYE16 (86% identical), SPDYE3 (65% identical), SPDYE12 (58% identical), SPDYE13 (58% identical), SPDYE14 (58% identical), SPDYE15 (58% identical), and 6 more.
Diseases named in the same sentence as SPDYE1 in open-access papers:
SPDYE1 is named in the same sentence as 2 diseases in open-access papers, as found by Europe PMC text mining. Sharing a sentence is not in itself a finding about the gene and the disease. The quoted sentences say what the papers report.
insomnia (1 paper, 2022). A sleep disorder characterized by difficulty in falling asleep and/or remaining asleep. "The SPDYE1 gene has no previous association to measures of sleep patterns and very little description of CNVs at this location; however, a related gene, SPDYE6, has been associated with insomnia via SNP GWAS in a much larger sample set (1.3 million samples)." (PMID 36779085, 2022).
SPDYE1 also shares sentences with these, for which no sentence is quoted: cancer (1 paper).